TERC (telomerase RNA component)
Diseases named in the same sentence as TERC in open-access papers (continued):
Sharing a sentence is not in itself a finding about the gene and the disease.
tumor (continued). "It is reported that consistent overexpression of TERC (the RNA component of telomerase) in PCa, driven by MYC, suggests a role in tumor progression." (PMID 41402347, 2025). "In human stem cells and approximately 85% of tumor cells, telomerase formed by TERT and TERC RNA complex is responsible for elongating telomeres." (PMID 40696438, 2025). "Of note, the low RNA levels of the telomere-related genes (less than five read counts), such as TERT and TERC, in both TCGA-LUAD and TCGA-LUSC tumour samples limited the direct comparison of these genes between these cohorts." (PMID 37079368, 2023). "Despite readily detectable TERC expression in normal cells, its upregulation occurs widely in TERT‐expressing tumours." (PMID 36394204, 2022). "SNHG3-203, TERC-201 and SNHG12-202 were upregulated, while ENST00000610809, ENST00000443132 and ENST00000619523 were downregulated in the EMPD tumor group." (PMID 34895219, 2021). "In paired t test analysis, all of the 4 genes (RAD50, RTEL, TERC and TRF1) showed significant expression (dCt) difference between tumor and normal tissues (with corrected P values of 1.22E-16, 7.78E-05, 1.08E-11 and 5.05E-13 respectively)." (PMID 28424414, 2017). "Twenty-seven of these were only polyploid; 22 were polyploid and amplified, with CEP3: TERC/SOX2 FISH ratios that varied from 3:6–8, to 3–4:9–12 to 4:6–11 in the same tumor." (PMID 24410919, 2014). "In tumour 26, the mRNA of the normal TERT isoform 1 was over-expressed at a high level but TERC was weakly expressed." (PMID 21170331, 2010). "Thus, the research and results link the markers regulating the tumor process and the telomerase complex TEP1 rs1760904, rs1713418, TERC rs12696304, rs35073794, TERT rs2736098, rs401681, which help explain the factors leading to the development of telocytes." (PMID 35892421, 2022). "CXCL8/IL8, ENA-78/CXCL5, IL6, and TERC/CCL25, both in double co-culture and triple co-culture, indicated the formation of a microenvironment with chronic inflammation characteristic of the tumor stroma and the active participation of MSCs in these processes." (PMID 36354566, 2022). "We found that TERC expression levels were not significantly different between tumor and adjacent nontumor tissues from BLCA patients but were significantly upregulated in urinary exosomes from BLCA patients compared with those from healthy controls." (PMID 35127956, 2022). "Reduction of the cellular material for the PCR validation also may well have reduced the repeatability of the tumor marker PCR assay and prevented validation of our LAMP assay for TERC/GAPDH and MYC GAPDH." (PMID 34790573, 2021). "In preclinical experiments, the overexpression of chicken TERC (cTERC) via genetically engineered Marek’s disease virus (MDV) containing cTERC instead of its viral TERC (vTERC), resulted in increased tumor incidence and visceral organ tumor load in chickens." (PMID 33599797, 2021). "Nevertheless, using a TERC-/- murine model importantly showed that lack of TERC results in telomere shortening, a higher incidence of tumor formation and accelerated aging." (PMID 30210531, 2018). "In our study, statistically similar levels of SOX2 and TERC amplifications occurred in all stages of the disease regardless of lymph node status and tumor classification." (PMID 24410919, 2014). "It has not been demonstrated that TERC is upregulated in tumor samples or cell lines in which it is amplified, and the correlation between the amplification and upregulation of the PIK3CA gene is still controversial." (PMID 22412903, 2012). "Interestingly, TERC and DKC1 overexpressions were observed to co‐occur in aggressive TCs,9 which raises the possibility of DKC1‐mediated stabilization of TERC RNA in these tumours." (PMID 36394204, 2022).
tumor (continued). "Although TERC has broad tissue distribution and is constitutively present in normal and tumor cells, the expression of TERT is usually repressed in normal somatic cells and is essential for unlimited cell growth, thus playing a critical role in tumor formation and progression." (PMID 29643934, 2018). "Increased TERT and TERC gene dosage has been detected frequently in a variety of human tumours, and clonal evolution of cells with increased TERT or TERC copy number has been observed, pointing towards a growth advantage in cells with increased TERT or TERC gene dosage." (PMID 29751586, 2018). "While TERC can be found in abundance in tumor and non-tumor cells, the catalytic subunit TERT is expressed in cells with self-renewal activity such as hematopoietic stem and progenitor cells (HSPCs), proliferating lymphocytes and the regenerative basal layer of the epidermis in human skin." (PMID 29143804, 2017). "Consistent with previous findings, the present study revealed higher expression levels of TERT and TERC, and increased TA and TL in CRC tumor tissue compared to adjacent non-tumor tissue." (PMID 39222177, 2025). "In the first, tumor was considered present if any tumor marker (hTERT n=7; TERC/GAPDH>3.12 n=6, MYC/GAPDH>0.155 n=7) was present with or without HPV positivity and tumor absent if all tumor markers were absent regardless of the presence or not of HPV." (PMID 34790573, 2021). "In the analysis of the 4 significantly hyper-methylated genes (RAD50, RTEL, TERC and TRF1), all of their expression levels were lower in tumor than the matched normal tissues, which suggested a negative correlation trend between methylation and expression." (PMID 28424414, 2017). "Surprisingly, neither the DN‐TERT nor the chemical inhibition of TERC with TAG 6 affected any function apart from telomerase activity per se, while BIBR 1532 reduced the expression of miR500A and, as a consequence, decreased tumour invasiveness in vivo." (PMID 33713376, 2021).
infection (6 papers, 2011 to 2024). The state of being infected such as from the introduction of a foreign agent such as serum, vaccine, antigenic substance or organism. "Although terC is known to function in tellurite resistance, the terC operon is also involved in the resistance to infection, tolerance to oxidative stress, resistance to phagocytosis by macrophages, the ability of cells to adhere to epithelial cells and filamentous bacterial cellular morphology." (PMID 39534302, 2024). "Activation of the non-LEE encoded factors such as aidA15, aidA48, iha, terC, toxB, ent/espL2, stcE, and nleA/B also aid the infection process by the pathogen." (PMID 21387009, 2011). "To test the role of the ter operon in a UTI, we competed our terC mutant and wild-type strains 1:1 in a well-established murine transurethral infection model." (PMID 36651775, 2023).
blood disorders (4 papers, 2019 to 2025). "Heterozygous variants in RTEL1, which encodes a protein involved in TERC processing and critical for telomere homeostasis, were also observed in hematological malignancies." (PMID 39940930, 2025). "As the CR4/CR5 domain of TERC is responsible for this noncanonical function, it was decided to design several aptamers based on the zebrafish CR4/CR5 terc domain to test its potential clinical usefulness in blood disorders." (PMID 37737237, 2023).
cardiovascular disease (2 papers, 2013 to 2022). "The haplotype of three SNPs within TERC was reported to be associated with an increased risk of cardiovascular diseases (CVDs) and T2DM in European Caucasians, and other TERC variants have been associated with longevity in humans." (PMID 36292740, 2022).
TERC also shares sentences with these, for which no sentence is quoted: multiple sclerosis (4 papers); progeria (3); acute myeloid leukemia (2); Infertility (2); Thrombocytopenia (2); adenocarcinoma (1); age (1); anemia (1); asbestosis (1); Autoimmunity (1); bacterial pneumonia (1); celiac disease (1); chronic kidney disease (1); chronic lymphocytic leukemia (1); colon cancer (1); Combined immunodeficiencies (1); congenital anemia (1); congenital neutropenia (1); COVID-19 (1); dementia (1); Dubowitz syndrome (1); E. coli infections (1); emphysema (1); endothelial dysfunction (1); ependymoma (1); esophageal cancer (1); essential hypertension (1); genetic diseases (1); Gestational Diabetes Mellitus (1); head and neck squamous cell carcinoma (1).
A further 30 diseases each share a sentence with TERC in 1 paper.